CRP (C-reactive protein)
Diseases named in the same sentence as CRP in open-access papers (continued):
Sharing a sentence is not in itself a finding about the gene and the disease.
unstable angina pectoris (16 papers, 2009 to 2023). "Aim of work: The purpose of this study was to demonstrate the utility of 2D-speckle tracking at rest and under stress along with hs-CRP for detection of CAD in patients who were referred to the chest pain unit with stable or low risk unstable angina pectoris." (PMID 35621834, 2022). "Preinfarct angina (95% CI: 1.61–5.65, P = 0.0005), plasma C-reactive protein (CRP) level (95% CI: 0.87–0.99, P = 0.016) and HCY < 17.55 μmol/L (95% CI: 2.43–8.72, P < 0.0001) were found to be independent predictors for SR." (PMID 29940881, 2018). "Lanza and colleagues assessed HRV and measured C-reactive protein (CRP) serum levels within 24 hours of admission in 531 patients with unstable angina pectoris." (PMID 22920474, 2013). "Furthermore, an AMI with myocardial necrosis will trigger an acute phase response with a subsequent rise in circulating CRP-levels, and elevated levels of CRP have also been reported in patients with both stable- and unstable angina pectoris." (PMID 34649504, 2021). "Preinfarct angina (95% CI: 1.61–5.65, P = 0.0005), plasma C-reactive protein (CRP) level (95% CI: 0.87–0.99, P = 0.016) and HCY < 17.55 μmol/L (95% CI: 2.43–8.72, P < 0.0001) were found to be independent predictors for SR on multiple logistic regression analysis." (PMID 29940881, 2018). "Also the rise in CRP after acute MI or during unstable angina pectoris has been shown to be related to outcome." (PMID 26631004, 2015). "Some studies suggest that inflammation may promote PC mobilization after acute ischemic events: CRP(C-reactive protein) correlates with the number of endothelial PCs in patients with unstable angina pectoris and interleukin-6 (IL-6) stimulates endothelial PCs at least in vitro." (PMID 24599235, 2014).
acne (15 papers, 2018 to 2025). An inflammatory process of the sebaceous glands which is characterized by comedones, nodules, papules and/or pustules on the skin. "Building on existing evidence, this study examines the relationship between serum and salivary levels of CRP, IL-17, and IL-19 in patients with acne vulgaris (AV), with a particular focus on their association with disease severity and scarring forms." (PMID 41465543, 2025). "The findings of our study highlight a strong association between acne severity and elevated levels of inflammatory (Hs-CRP, IL-6) and oxidative stress (MDA) markers, supporting their role in the pathogenesis of the disease." (PMID 40851686, 2025). "Acne vulgaris (AV) is a chronic inflammatory skin disorder, and cytokines such as interleukin-17 (IL-17), interleukin-19 (IL-19), and C-reactive protein (CRP) are thought to contribute to its immunopathogenesis." (PMID 41465543, 2025). "One trial focused on PCOS and found superiority of simvastatin in effects on lipids, CRP, and acne; metformin performed better in terms of effects on blood sugar and insulin measures." (PMID 40808694, 2025). "We also found that Hs-CRP was significantly elevated in moderate (2.64±0.80) and severe (3.0±0.10) acne, with a significant positive correlation, especially in the severe group (r=0.137, p=0.009), as measured by GAGS." (PMID 40851686, 2025). "Taken together, CRP, IL-19, and IL-17 display a consistent pattern in our cohort: none showed severity-related systemic elevation despite their known local roles in acne pathophysiology." (PMID 41465543, 2025). "Relatively normal serum hsCRP levels have been observed in acne vulgaris (mean approx. 2.2 mg/L, values 0–28), whereas another studies highlighted serum and salivary CRP as potential markers of the condition and a marker for post-acne scarring." (PMID 37873776, 2023). "The area under the curve (AUC) value of the CRP/albumin ratio in the receiver operating characteristic (ROC) analysis between the acne and control groups was 0.660, and its cut-off value was found to be 0.236 with 68.6% sensitivity and 68.9% specificity." (PMID 37750127, 2023). "Patients with acne conglobata also exhibited significantly higher CRP levels than patients with acne papulopustulosa and comedonica (p < 0.001, respectively)." (PMID 37892480, 2023). "CRP was significantly higher in the control group than in the acne group (p=0.014)." (PMID 37750127, 2023). "With the clinical trial focus on fever, CRP POCT may also miss patients who use antibiotics for conditions like acne and muscle pain." (PMID 29499522, 2018). "However, when we look at the CRP values of the acne group, some patients had higher CRP levels, but most of the acne patients (51 out of 61 acne patients) had mild or moderate acne severity index, which may not cause an increase in CRP level." (PMID 37750127, 2023). "In acne pathogenesis, IL-1, IL-6, and tumor necrosis factor-alpha (TNF-α)—major inflammatory mediators—stimulate CRP production in the liver." (PMID 41465543, 2025). "The primary objective of this study was to estimate inflammatory markers such as high-sensitive C-reactive protein (Hs-CRP), interleukin-6 (IL-6) and an oxidative stress marker, malondialdehyde (MDA), in acne patients." (PMID 40851686, 2025). "In our cohort, neither IL-19 nor CRP demonstrated a severity-related systemic increase, supporting the interpretation that the inflammatory activity in acne vulgaris is predominantly localized rather than strongly systemic." (PMID 41465543, 2025). "Consistent with several previous studies, our findings did not reveal a significant difference in CRP levels among control group and patients with moderate to severe acne vulgaris, regardless of gender." (PMID 41465543, 2025). "CRP/albumin ratio and MCR may serve as inflammatory markers that can be used to monitor the severity of acne vulgaris." (PMID 37750127, 2023).
acne (continued). "Studies on acne vulgaris likewise suggest absence of systemic inflammatory response, estimated by C-reactive protein (CRP) level, even in severe cases." (PMID 30473726, 2018). "The elevated levels of Hs-CRP observed in severe-grade acne in our study may be attributed to the increased number of inflammatory lesions and the concurrent elevation of cytokines such as IL-6 and TNF-α, which stimulate the hepatic production of CRP." (PMID 40851686, 2025). "However, two studies conducted in 2014 and 2015 found no significant increase in CRP levels in acne vulgaris patients." (PMID 41465543, 2025). "Additionally, the lack of a severity-related increase in serum CRP—an established marker of systemic inflammation—indicates that the inflammatory activity in acne vulgaris remains largely local rather than systemic." (PMID 41465543, 2025). "We found that the co-administration of vitamin D and probiotic for 12 weeks to women with PCOS had beneficial effects on mental health parameters, serum total testosterone, hirsutism, hs-CRP, plasma TAC, GSH and MDA levels, but did not affect serum SHBG, plasma NO levels, acne and alopecia." (PMID 30665436, 2019). "Overall, the co-administration of vitamin D and probiotic for 12 weeks to women with PCOS had beneficial effects on mental health parameters, serum total testosterone, hirsutism, hs-CRP, plasma TAC, GSH and MDA levels, but did not affect serum SHBG, plasma NO levels, acne and alopecia." (PMID 30665436, 2019).
arterial disease (15 papers, 2007 to 2025). "In conclusion, CRP in patients with RA is unrelated to structural measures of subclinical arterial disease and there is a paradoxical association of CRP with improved endothelial function." (PMID 20436910, 2010). "The C-reactive protein–albumin–lymphocyte (CALLY) indexis a novel inflammatory biomarker, and its association with the prognosis ofcoronary artery disease (CAD) after percutaneous coronary intervention (PCI) hasnot previously been studied." (PMID 39076545, 2024). "CRP levels were correlated withperipheral artery disease severity in patients undergoing LEBS." (PMID 19360107, 2009). "CRP has previously been identified as a risk factor for arterial disease in SLE, but we were not able to replicate those results." (PMID 20003285, 2009).
gastritis (15 papers, 2014 to 2025). Inflammation of the stomach. "However, as serum CRP also increases as a result of exercise or general illness in sleds dogs, the use of serum CRP as a general diagnostic tool for gastritis or gastric ulceration may be limited in racing sled dogs." (PMID 27112583, 2016). "Among the inflammatory indicators, the changes in white blood cell count, C-reactive protein and erythrocyte sedimentation rate profoundly reflect the key role of inflammatory response in the prognosis of gastritis." (PMID 40800140, 2025). "A recent post hoc analysis of the CONDOR trial showed that baseline C-reactive protein levels, history of gastritis and of GI intolerance, H. pylori infection, old age, and body mass index were all associated with clinically significant blood loss in OA patients treated with NSAIDs." (PMID 25857826, 2015). "Peptic ulcer disease or gastritis was considered due to the pain’s location and vomiting, but normal amylase and CRP levels, along with no history of NSAID use or gastrointestinal symptoms, made this unlikely." (PMID 41210009, 2025). "Rahmaniet al.12 found that although the presence of atrophy or metaplasia did not affectserum hs-CRP levels, gastritis patients having dysplasia had significantly higherhs-CRP level than patients without dysplasia." (PMID 30916140, 2019). "Thus, we noticed significantly higher values of CRP values in TT carriers with H. pylori-negative gastritis when compared to those with H. pylori-induced gastritis (p = 0.0264) or healthy controls carrying the same genotype (p = 0.0137)." (PMID 35204842, 2022). "The possible inflammatory markers that can be used to evaluate gastritis are the interleukin family—mainly IL-6—and other proinflammatory cytokines, namely the tumor necrosis factor alpha (TNF-α), IL-1, and IL-8, C-reactive protein (CRP), platelets and neutrophils." (PMID 32722268, 2020).
Hepatosplenomegaly (15 papers, 2014 to 2026). Simultaneous enlargement of the liver and spleen. "Certain clinical signs (such as eschar and hepatosplenomegaly) and routine laboratory markers (particularly CRP) provided valuable discriminatory power, helping to distinguish bacterial and rickettsial infections from viral causes." (PMID 42093780, 2026). "Previous studies have demonstrated that HMGB1 levels were related to destructive JIA and more sensitive than CRP in detecting hepatosplenomegaly or serositis among patients with systemic JIA." (PMID 34247641, 2021). "This is corroborated by the fact that although the CRP levels in systemic JIA patients presenting with hepatosplenomegaly or serositis were very high, HMGB1 was a more sensitive indicator (a diagnostic sensitivity for HMGB1 was 94% while for CRP was 64%)." (PMID 25516724, 2014). "Compared to the BCG-itis group, the BCG-D group exhibited significantly higher rates of fever, hepatosplenomegaly, elevated white blood cell counts, neutrophil counts, and C-reactive protein (CRP) levels, along with lower red blood cell counts and hemoglobin levels (p<0.05)." (PMID 40470261, 2025). "However, children in the BCG-D group exhibited a higher proportion of fever and hepatosplenomegaly, as well as elevated white blood cell counts, neutrophil counts, and C-reactive protein levels." (PMID 40470261, 2025). "The CRP levels of systemic JIA patients presenting with hepatosplenomegaly or serositis were also significantly higher but HMGB1 was more sensitive than CRP in detecting hepatosplenomegaly or serositis in these patients, as shown by receiver operating characteristics (ROC) curve assessment." (PMID 25516724, 2014).
kidney (15 papers, 2013 to 2024). "High baseline CRP in healthy patients carries an increased risk of future cancer development, although genitourinary cancers specifically have not been shown to be significantly correlated with CRP." (PMID 34512646, 2021). "Despite the abundance of correlative studies, the relationship between CRP levels and genitourinary cancer pathogenesis is not clearly understood." (PMID 34512646, 2021).
mediastinitis (15 papers, 2012 to 2025). An inflammatory process affecting the mediastinum. "Paraclinical tools at the onset of mediastinitis signs showed elevated white blood cell counts and C-reactive protein levels in most cases." (PMID 40718069, 2025). "Our study demonstrated that the impact of the increased levels of cytokines and CRP on postoperative pain presented only at the baseline time point in the group with mediastinitis." (PMID 37637509, 2023). "In the present study, we aimed to investigate the relationship between mediastinitis and persistently elevated cardiac-specific biomarkers [troponin T (TnT) and N-terminal pro-brain natriuretic peptide (NT-proBNP)] and C-reactive protein (CRP) at mid-term follow-up following CABG." (PMID 36824453, 2023). "C-reactive protein (CRP) level and white blood cell (WBC) count for bothgroups measured at the time of post-sternotomy mediastinitis (PSM) diagnosisand discharge." (PMID 36692043, 2023). "Some authors found that patients ≥ 55 years old, CRP ≥ 30 mg/dL, and neutrophil to lymphocyte ratio ≥ 13 prior to DNI management were analytic predictors of progression to descending mediastinitis." (PMID 37685275, 2023). "A similar pattern was seen for TnT with the highest levels in those with mediastinitis 14.7 (±6.8) ng/l vs. 11.2 (±2.7) ng/l (mean ± SD, p = 0.004), but not for CRP (p = 0.14)." (PMID 36824453, 2023). "Some authors even found that increased CRP levels were a negative factor for the survival of patients with surgical treatment for descending mediastinitis in the postoperative period." (PMID 37685275, 2023). "Persistent mediastinitis per se as an inflammatory condition could potentially be a contributing factor, but the lack of difference in CRP levels between the two groups, makes this possibility unlikely." (PMID 36824453, 2023). "In the present study we showed that patients with VAC-treated mediastinitis after CABG, had significantly higher serum levels of NT-proBNP and TnT, but not of CRP, compared with patients without mediastinitis even 2.7 years (median) following CABG." (PMID 36824453, 2023). "Therefore, in the present study, we examined the levels of NT-proBNP, TnT and CRP following CABG in patients with and without complicating mediastinitis." (PMID 36824453, 2023).
normocytic anemia (15 papers, 2014 to 2026). Anemia in which the red blood cell volume is normal. "Laboratory tests revealed normocytic anemia, leukocytosis with neutrophilia, C-reactive protein (CRP) of 38.15 mg/dL, elevated alkaline phosphatase (ALP), and gamma-glutamyl transferase (GGT)." (PMID 40027026, 2025). "Laboratory investigations revealed normocytic anemia (hemoglobin, 100 g/L), hypoproteinemia (albumin, 33.7 g/L), elevated inflammatory marker levels (CRP, 13.77 mg/L; ESR, 50 mm/h), and a high platelet count of 320 × 109/L." (PMID 37798676, 2023). "Laboratory investigations revealed normocytic anemia (hemoglobin, 97 g/L), hypoproteinemia (albumin, 29.6 g/L), and elevated inflammatory marker levels [C-reactive protein (CRP), 10.47 mg/L; erythrocyte sedimentation rate (ESR), 28 mm/h]." (PMID 37798676, 2023). "Laboratory testing showed normocytic anemia (Hgb 13 g/dl), a peripheral white cell count of 11,800/μl (with 85% neutrophils), an ESR of 50 mm, CRP 13.5 mg/dl, AST 52 IU/l and ALT 75 IU/l." (PMID 28978355, 2017). "Laboratory testing revealed normocytic anemia (Hb 11.2 g/dl), a peripheral white cell count of 16,600/μl (with 82% neutrophils), an erythrocyte sedimentation rate (ESR) of 89 mm, C-reactive protein (CRP) 13 mg/dl (normal up to 5), AST 54 IU/l and ALT 73 IU/l." (PMID 28978355, 2017).
Opportunistic infection (15 papers, 2010 to 2025). An infection that is caused by a pathogen that would generally not be able to cause an infection in a host with a normal immune system. "Markers of inflammation that remain elevated include interleukin-6 (IL-6), C-reactive protein (CRP), and D-dimer, and have been associated with all-cause mortality and opportunistic infections." (PMID 38455337, 2022). "Thus, the CRP level increases with increase in opportunistic infection that makes CRP a better diagnostic biomarker that may reflect the immune suppression of the host." (PMID 39834358, 2025). "C-reactive protein is acute phase protein which is increasingly seen in PLWH as a result of opportunistic infections." (PMID 39834358, 2025). "Even though cytomegalovirus and cryptosporidium were only isolated in one patient with SCID4-IL2RG and one with HIGM1-CD40L, both had persistent cramping pain and high CRP levels, implying possibly mixed bacterial pathogens in such opportunistic infections." (PMID 28623282, 2017). "Moreover, CRP would not replace diagnostic testing for TB or other opportunistic infections and noncommunicable diseases." (PMID 39022393, 2024). "The inflammatory marker CRP, when measured with high sensitivity assays, is a known predictor of cardiovascular events in the general population, and among treated HIV-infected patients, has been associated with cardiovascular events and opportunistic infections." (PMID 20949133, 2010). "In the patients with and without active opportunistic infection during the past 30 days, 75% and 38% had higher CRP level from the normal range, respectively." (PMID 26727515, 2016). "However, in settings without access to mycobacterial culture and chest radiographs, the detection of a high CRP level (>5 mg/L or >10 mg/L, for example) can alert providers to a potential case of TB or other opportunistic infection, even if sputum smear or Xpert MTB/RIF testing is negative." (PMID 39022393, 2024). "An increment in the level of CRP is independent of the stage of HIV infection and thus is useful for supporting a diagnosis of opportunistic infections in HIV-coinfected patients." (PMID 21197091, 2011). "CRP was higher among cART-treated HIV-infected than age-matched healthy HIV-negative adults from the same communities; despite more than twelve years of suppressive cART, restoration of CD4 counts to at least 500 cells/μl and no opportunistic infections within the 6 months preceding our study." (PMID 34445953, 2021).